MIR1469 (microRNA 1469)
Synonyms: hsa-mir-1469; MIRN1469
Gene: MicroRNA gene on chromosome 15 (96,333,261 to 96,333,307, forward strand). Ensembl gene ENSG00000283888.
Homologues: Orthologues: chimpanzee MIR1469 (100% identical), macaque MIR1469 (100% identical).